INS (insulin)
Diseases named in the same sentence as INS in open-access papers (continued):
Sharing a sentence is not in itself a finding about the gene and the disease.
diabetes (continued). "Diabetes is a group of metabolic disorders characterized by chronic hyperglycaemia due to pancreatic β-cells failure and consequent inability to secrete the appropriate amount of insulin to meet the needs of the organism." (PMID 32286361, 2020). "This may be the reason why the largest immediate effects of the new SRS were seen among patients utilizing only other diabetes medications than insulin or metformin in 2016 in this study." (PMID 33246453, 2020). "According to Evans, saffron extract contains ingredients with antioxidant actions, which may alleviate decreased insulin secretion and impaired insulin resistance and protect tissues against diabetes complications." (PMID 33367177, 2020). "The disturbance of neurogenic glucose metabolism caused by impaired insulin signaling results in AD characteristics that parallel the pathophysiology of non-nervous tissues in type 2 diabetes mellitus." (PMID 33250703, 2020). "Rg3 improves insulin secretion, which is important in the treatment of diabetes." (PMID 32161549, 2020). "Most of the studies used insulin initiation as a marker of diabetes progression." (PMID 32318630, 2020). "Difficulties may arise from practical decisions about packing insulin properly and bringing spare diabetes-related supplies (e.g. meters, sensors, pumps, needles, glucagon, snacks, etc.)in carry-on luggage." (PMID 32533229, 2020). "The main feature of type 1 diabetes mellitus is the lack of insulin and of C-peptide, but the progressive β-cell loss is also observed in later stage of type 2 diabetes mellitus." (PMID 31963760, 2020). "Diabetes mellitus (DM) represents a global health problem, touching more than 400 million people and consists of a group of metabolic disorders characterized by persistent hyperglycemia arising from impaired insulin secretion, insulin action, or both." (PMID 32456137, 2020). "Therefore, our findings indicated that treatment of PUFA improved glucose and insulin tolerance in pregnant rats with diabetes." (PMID 33110438, 2020). "It has been found that the loss of Nkx6.1 causes rapid-onset diabetes due to defects in insulin biosynthesis and secretion without affecting on β cell survival." (PMID 33121533, 2020). "In T1D diabetes, exogenous insulin therapy is required to sustain life; in T2M, insulin may be viewed by patients as optional to delay complications." (PMID 31833010, 2020). "Patients with diabetes are unable to produce or properly use the hormone insulin." (PMID 32106464, 2020). "Mostly, these induced insulin-producing cells were functional and could slightly change the consequences of chemically-induced diabetes." (PMID 32235681, 2020). "Numerous physiological studies had declared that free radicals might contribute to the autoimmune destruction of pancreatic β cells, leading to diabetes, and may impair insulin action." (PMID 32405356, 2020). "In addition, the experience of using telemonitoring to facilitate the transition to insulin therapy was explored from the perspective of the diabetes team and health care organization." (PMID 32406854, 2020). "In the last few decades, the improvement of diabetes therapy (education, use of insulin and /or its analogues and delivery technology) may have suggested that MS was about the past in the history of diabetes." (PMID 32600434, 2020). "We suggest that PKR inhibitor treatment may be used to increase the insulin secretion capacity of the pancreas in later stages of diabetes." (PMID 32256145, 2020). "This could be closely related to the progress in diabetes education, continuous monitoring of blood sugar, the widespread use of insulin and insulin analogues, and sensor-augmented pump therapy." (PMID 32901098, 2020). "Interestingly, two US studies found a decrease in number of diabetes medications after dementia diagnosis, while Weiner and colleagues reported higher use of insulin in patients with poorer health and longer diabetes duration." (PMID 32741836, 2020).
diabetes (continued). "There were less newly diagnosed diabetes among patients on insulin treatment." (PMID 32267843, 2020). "After adjusting for multiple confounding factors, including gender, age, education, duration of diabetes, baseline insulin regimen, and baseline FBG and PBG, multivariate linear regression analysis showed that the number of diabetes education courses completed was still related to both FBG and PBG." (PMID 32141838, 2020). "Patients with IR and compensatory increase in insulin secretion may develop diabetes mellitus in later life when the ability to secrete insulin declines." (PMID 31989990, 2020). "Published data from the American Diabetes Control and Complication Trial (DCCT) indicated that a 1.9% decrease in HbA1c through early intensive insulin treatment could significantly decrease the risk of complications and death." (PMID 32548087, 2020). "In subgroup analyses, stronger point estimates for immediate changes in HbA1c levels at the time of the policy change than in the primary analysis were detected among patients utilizing only other diabetes medications than insulin or metformin in 2016 (3.56 mmol/mol, 95% CI 2.50–4.62)." (PMID 33246453, 2020). "In order to examine the effects of CrPic on diabetes, blood glucose and serum insulin was detected." (PMID 32143429, 2020). "The Chinese medical herb kudzu root has been used for the treatment of diabetes mellitus for a long time, and several previous studies have shown that puerarin has a pharmacological effect of improving glucose uptake and attenuating insulin sensitivity." (PMID 32946041, 2020). "Interestingly, the Metformin in Gestational Diabetes (MiG) study showed a higher acceptability for metformin than insulin, despite the gastrointestinal side effects produced by metformin." (PMID 32625081, 2020). "Over 90% of diabetes mellitus cases are T2DM, a condition marked by deficient insulin secretion by pancreatic islet β-cells, tissue insulin resistance (IR) and an inadequate compensatory insulin secretory response." (PMID 32872570, 2020). "Dogs with diabetes mellitus on insulin treatment for at least 1 month were included." (PMID 33124730, 2020). "Other diabetes-related apps address multiple aspects of diabetes self-management, including tracking of glucose data, physical activity, diet, and insulin doses; such apps may also include assistance with carbohydrate counting." (PMID 33112249, 2020). "By controlling Met levels, the conditions of glucose homeostasis, insulin sensitivity, and oxidative stress with activation of the fibroblast growth factor 21 and protein phosphatase 2A signals in diabetes may improve." (PMID 33319826, 2020). "The term diabetes mellitus describes a metabolic disorder of multiple etiology, characterized by chronic hyperglycemia with disturbances of carbohydrate, fat, and protein metabolism resulting from defects in insulin secretion, insulin action, or both." (PMID 32142224, 2020). "Diabetes is closely related to obesity, a group of metabolic disorders characterized by high blood sugar levels over a prolonged period resulting from either destruction or impairment of insulin-secreting pancreatic cells and insulin action in target tissues." (PMID 33266423, 2020). "Diabetes mellitus is a chronic metabolic disease characterized by the presence of high blood glucose levels (hyperglycemia) due to a quantitative or qualitative deficit of insulin effect." (PMID 33218062, 2020). "Diabetes is a chronic metabolic disorder triggered by disturbances in carbohydrate, protein, and lipid metabolisms, where either reduced secretion or sensitivity of insulin is observed coupled with poor glucose control." (PMID 33126433, 2020). "Therefore miR-184 has the potential for involvement in the pathogenesis of diabetes by reducing the level of glucose-induced insulin secretion." (PMID 32457801, 2020). "Likewise, glutamine, through GLP-1 mediation and in a dose-dependent manner, increases insulin release in diabetes mellitus." (PMID 32983244, 2020).
diabetes (continued). "This includes ascertainment of diabetes type, although we adapted previously validated algorithms to be more specific for type 1 diabetes by including not only diagnosis codes but also medications (eg, insulin use)." (PMID 31922562, 2020). "Characterized by hyperglycemia, diabetes mellitus (DM) is a group of chronic, metabolic diseases in which the pancreas does not secrete enough insulin, a hormone regulating blood sugar, and/or the body develops resistance to insulin it produces." (PMID 32824886, 2020). "DM in these patients might resemble more closely type 2 diabetes mellitus (T2DM) with excess insulin and peripheral insulin resistance." (PMID 33228173, 2020). "Among adults aged 18 years or older, the self-reported prevalence of hypertension was 17.2% (95% CI, 15.9%-18.6%), that of diabetes (both insulin dependent and non–insulin dependent) was 9.8% (95% CI, 8.6%-11.1%), and that of both conditions was 7.3% (95% CI, 6.3%-8.5%)." (PMID 33052405, 2020). "Therefore, the ideal treatment for diabetes should restore both insulin production and insulin secretion regulation by glucose in patients." (PMID 32641151, 2020). "Traditional diabetes care includes insulin delivery using syringes, pens, or pumps." (PMID 32484447, 2020). "A better understanding of the role of NO system in the regulation of insulin secretion may facilitate the development of new therapeutic strategies in the management of diabetes." (PMID 33088259, 2020). "Importantly, histidine, a precursor amino acid for histamine was observed to improve insulin sensitivity and ameliorate metabolic syndrome, hence, by regulating hepatic glucose output, it can assist in the glycemic control in diabetes." (PMID 32349282, 2020). "Hourly and daily analyses were conducted by analyzing the deviations incurred on the key diabetes parameters, blood glucose levels, insulin, carbohydrate, and the insulin-to-carbohydrate ratio as a result of infection incidence in contrast to the whole patient year." (PMID 32784178, 2020). "The short Tmax and the 120-min duration of effect of oral insulin spray suggest it may be a promising alternative for fulfilling meal-related insulin requirements in persons with diabetes." (PMID 32349416, 2020). "Thus, VAT/m3 appears to provide better indications of metabolic characteristics (insulin sensitivity and pre-diabetes/diabetes) than VAT volume alone." (PMID 32664590, 2020). "Type 2 diabetes mellitus (T2DM) is a multifactorial metabolic disease that occurs either when the pancreas does not produce enough insulin or when the body cannot effectively use the insulin it produces." (PMID 33096688, 2020). "Another study found that long-term innate immune activation could impair insulin secretion and action, and play an important role in the pathology of diabetes." (PMID 33123093, 2020). "Further, ASBT inhibitors have been shown in both humans and animal models to improve insulin sensitivity in diabetes, which may at least in part be attributed to the induction of gut glucagon-like peptide 112,55,56." (PMID 32681035, 2020). "Chronic stimulation of β2-adrenoceptors, opposite to acute treatment, was reported to reduce blood glucose levels, as well as to improve glucose and insulin tolerance in rodent models of diabetes by essentially unknown mechanisms." (PMID 32472192, 2020). "However, the largest immediate increase (3.56 mmol/mol, 95% CI 2.50–4.62, or 0.33%) was observed among patients utilizing only other diabetes medications than insulin or metformin in 2016." (PMID 33246453, 2020). "These variables were moderately correlated and insulin treatment was not independently associated with hypoglycemia (OR 0.80, 95% CI: 0.37 to 1.71, P = 0.56) when diabetes status was included in the multivariable model." (PMID 33328554, 2020).
diabetes (continued). "A closed-loop system imitating the function of pancreatic cells, connected to microneedles (MNs) that automatically “release” insulin in response to the blood glucose (BG) levels would be highly satisfactory for improving the quality of life and health for diabetes patients." (PMID 32629825, 2020). "α-Glucosidase and PTP1B are the key targets to treat diabetes and obesity and compounds with dual inhibitory activity against these enzymes exhibit synergistic effects to prevent hyperglycaemia, in turn, effectively improve insulin sensitization." (PMID 32156083, 2020). "This has yet to be proven in the diabetic trauma patient; therefore, our study would serve as the initial step in establishing an insulin regimen for diabetic trauma patients, especially in the Hispanic patient population, which is disproportionately affected by diabetes." (PMID 30478726, 2020). "Insulin resistance appears due to the reduced ability of the insulin receptor to respond to insulin stimulation, this resistance being a major feature of diabetes that could be detected long before the clinical signs of the disease." (PMID 32503113, 2020). "Interestingly, insulin resistant Zucker Diabetic Fatty rats, PP2A mRNA is increased in liver, muscle and adipose tissue, thus suggesting a role for the phosphatase in deregulating insulin signaling in T2DM." (PMID 32630698, 2020). "Moreover, it has been demonstrated that a high-monounsaturated-fat, low-carbohydrate diet improves insulin sensitivity peripherally in non-insulin-dependent diabetes mellitus subjects." (PMID 32543351, 2020). "PTP1B, on the other hand, is an intracellular non-receptor protein tyrosine phosphatase, which is highly expressed in insulin targeted tissues such as liver and muscle including fats and has also received much attention due to its role in type 2 diabetes mellitus and obesity." (PMID 32156083, 2020). "Also, a decrease in the first phase of GSIS is found in the initial stage of T2DM and prediabetes condition that represents β-cells dysfunction, and the second phase of insulin release is destroyed following the progression of diabetes." (PMID 32831835, 2020). "Previous studies have reported other pancreatic lineages that may be used to generate insulin-secreting cells for diabetes treatment." (PMID 31979403, 2020). "It is generally believed that diabetes is caused by a lack of insulin secretion activity or insulin resistance." (PMID 33292335, 2020). "Individuals with this microvascular complication diagnosed by this tool presented more severe diabetes (as shown by a higher frequency of insulin use) and classical risk factors for DSP, such as longer diabetes duration, worse glycemic control and a higher stature." (PMID 32384735, 2020). "Diabetes is a multi-etiological chronic metabolic disorder that is primarily characterized by pathological and physiological changes induced by insulin resistance and impaired insulin secretion." (PMID 33643038, 2020). "This could help patients with diabetes mellitus get rid of the dependence on exogenous insulin and obtain better compliance." (PMID 32850735, 2020). "Measuring DEBs using a generic DEB tool may fail to identify or inaccurately assess certain diabetes-specific eating behaviors, such as insulin omission or reduction." (PMID 33292623, 2020). "Currently, an FDA-approved analogue of human IAPP (containing several amino acid substitutions that prevent it from aggregation) named Pramlintide is prescribed for mealtime usage for patients affected from diabetes under insulin prescription in order to fulfil IAPP missing functions." (PMID 32131431, 2020). "Diabetes mellitus is a common endocrine and metabolic disease caused by the lack of insulin secretion in the body, leading to disorders of protein and fat metabolism caused by hyperglycemia." (PMID 31257946, 2019).
diabetes (continued). "Finally, we confirmed that isolated hUDSCs are capable of differentiating into insulin-producing β-cells and suitable for use in the treatment of diabetes." (PMID 31839754, 2019). "Disorder of Cdc42 will impair normal insulin secretion and contribute to diabetes." (PMID 30621321, 2019). "Again, the type 2 diabetes status of our participants is important here, as the presence of diabetes may have attenuated any pre-morbid ethnic differences in insulin sensitivity." (PMID 30729259, 2019). "The biocompatible nanogels with intelligent glucose-induced insulin release ability may have potential applications in diabetes therapy." (PMID 30893913, 2019). "As insulin is typically prescribed in diabetes cases with severely impacted glucose controls, effects of disease may outweigh the effects of the agent." (PMID 31693707, 2019). "This approach may become of particular importance under insulin-resistant conditions, such as diabetes mellitus, in which the glucose utilization is further impaired in response to various stimuli, including insulin stimulation as well as ischemic insult." (PMID 31262297, 2019). "We found that in the first 90 days after insulin initiation, the vast majority of patients continued their previous non-insulin therapy, including 84.6% of patients continuing metformin and 78–82% of patients continuing newer diabetes medications." (PMID 30759121, 2019). "Many healthcare providers face significant challenges of advising patients with type 1 diabetes mellitus who insist on fasting regarding the appropriate choice and adjustment of their insulin regimens, as well as the timing of breaking the fast during Ramadan7." (PMID 30938074, 2019). "Given that use of insulin might represent the more advanced stages of diabetes, this may have contributed, in part, to the poorer OS observed in this group compared to the metformin group." (PMID 31139216, 2019). "Here the authors present a blood-based EWAS of fasting glucose and insulin among 4808 non-diabetic Europeans and identify nine CpGs not previously implicated in glucose, insulin homeostasis and diabetes." (PMID 31197173, 2019). "Results suggest that miR-449a-Jag1 interaction is critical in Notch signalling and insulin signalling in the skeletal muscle and modulating this interaction might hold therapeutic potential for impaired skeletal muscle metabolism during diabetes." (PMID 31345231, 2019). "Furthermore, although we accounted for HbA1c and prior insulin use, we were unable to adjust for other indicators of quality of diabetes management, including microvascular and other macrovascular complications, as these data were unavailable." (PMID 31815634, 2019). "Insulin mimetics used as oral diabetic agents, which act similar to insulin but do not synthesize fats, have been suggested as a good solution for the treatment for diabetes." (PMID 30783120, 2019). "Our data suggest that low expression of transgenic insulin could function as a complement to insulin injections, and has the potential to improve quality of life in people with diabetes." (PMID 30514969, 2019). "In this review, we included animal in vivo and human reports about the role MO may play in diabetes, focused on changes in glycaemia and insulin." (PMID 31810205, 2019). "The emergence of MetS in type 1 diabetes might be attributed to advanced age, duration of diabetes, renal function, and insulin therapy, all of which were independently relevant to MetS." (PMID 31049079, 2019). "This bifunctional role of p110α may, in part, explain the association between muscle insulin resistance and mitochondrial dysfunction in diabetes and other insulin-resistant states." (PMID 31363081, 2019). "A Danish study found that for all cancers combined and diabetes duration of 2 years at cancer diagnosis, patients treated with insulin experienced the highest mortality rate ratios starting from 3.7 for men and 4.4 for women one year after the cancer diagnosis." (PMID 31185995, 2019).